PTPN11 (protein tyrosine phosphatase non-receptor type 11)
Diseases named in the same sentence as PTPN11 in open-access papers (continued):
Sharing a sentence is not in itself a finding about the gene and the disease.
tumor (continued). "A recent study also reported endothelial deletion of PTPN11 and pharmacological inhibition could lead to tumor vascular normalization and significantly reduce the tumor growth." (PMID 35802774, 2022). "Furthermore, PTPN11 is crucial in regulating the PI3K-Akt signaling pathway to facilitate tumor cell proliferation." (PMID 35802774, 2022). "However, higher protein phosphorylation levels of Y584 of PTPN11 was noted in tumor tissues of clear cell RCC." (PMID 35802774, 2022). "In conclusion, this is the first study that shows PTPN11 is aberrantly expressed in multiple types of cancer and clarifies how PTPN11 expression correlates with survival of tumor patients, protein phosphorylation, TMB, MSI, MMRs, and immune cell infiltration in multiple cancers." (PMID 35802774, 2022). "HMGA1 (i.e., upregulated in tumor MF) and PTPN11/SHP2 (i.e., downregulated in MF) were selected." (PMID 34831413, 2021). "Furthermore, genetic deletion of PTPN11 or inhibition of SHP2 in KRAS-mutant-driven tumors delays tumor progression." (PMID 33777940, 2021). "For example, one patient had a PTPN11 mutation thought to drive EGFR addiction and, hence, response to afatinib, and another patient had a tumor that was EGFR amplified and carried an additional allele on the amplicon, potentially underlying the sustained response observed." (PMID 34787778, 2021). "We created a Ptpn11 LOH mouse model in PRRX1-expressing cells, and found that SHP2 deficiency in PRRX1+ OCPs was involved in the pathogenesis of cartilage lesions, indicating that SHP2 functions as a tumor suppressor in cartilage and is required in OCPs for cartilage development and homeostasis." (PMID 29644115, 2018). "Furthermore, PTPN11 has been identified to act as a tumor suppressor in hepatocellular carcinogenesis." (PMID 28750679, 2017). "In particular for PTPN11, the variant was frequently detected in the lymphocyte “normal” sample, suggesting that these are a result of tumor-in-normal contamination, or variants that are either germline or mosaic." (PMID 29146900, 2017). "In contrast, PTPN11 has a tumor-suppressor function in liver and cartilage." (PMID 26768750, 2016). "Most recent experimental data suggest that in contrast to the proto-oncogene effect of dominant-active mutants, PTPN11 may act as a tumor suppressor in hepatocarcinogenesis." (PMID 25198338, 2014). "However, most recent findings suggest an unexpected tumor suppressor role of PTPN11 in HCC, implying its dual faces in tumorigenesis." (PMID 25198338, 2014). "Furthermore, disruption of the ITSM region prevented PD-1-mediated inhibition of TCR-driven proliferation and cytokine production, whilst a vital role for PTPN11 in immune checkpoint receptor function in tumour-infiltrating leukocytes (TILs) has been suggested." (PMID 38334623, 2024). "In addition, one patient with brainstem ganglioglioma and dysmorphic features (patient #4) had PTPN11 alteration in her tumor, which was confirmed on germline testing to have the heterozygous pathogenic mutation leading to a diagnosis of RASopathy spectrum disorder." (PMID 38440233, 2024). "Moreover, in the tumour sample, several mutations, in BRAF1 and PTPN11 were found." (PMID 37843608, 2023). "Therefore, we assumed that MF exerted its excellent anti-tumor capacity via targeting PTPN11." (PMID 37892971, 2023). "Taken together, it was shown that MF could target PTPN11 to exert anti-tumor activity." (PMID 37892971, 2023). "Accordingly, PTPN11 could be regarded as an effective target for tumor therapy in HNSCC." (PMID 37892971, 2023). "Thus, we reasonably assumed that a single usage of MF could target PTPN11 to produce a marked anti-tumor effect." (PMID 37892971, 2023). "Besides, the Kaplan-Meier plotter data suggested the higher PTPN11 expression was related to poorer survival prognosis in most cancers, which strongly indicates PTPN11 may represent a unique marker and therapeutic target for tumor treatment." (PMID 35802774, 2022).
tumor (continued). "The same deleterious c.1520 C>A variant in PTPN11 was detected in the FFPE tumor tissue (with a VAF of 36%), and was nearly absent in buccal swab and blood DNA (<0.2%) and could not be distinguished from background sequencing errors." (PMID 35778969, 2022). "Furthermore, PTPN11 is published to be in complex with JAK2 upon cytokine-induction in tumor cells." (PMID 33247204, 2021). "Similarly, knockout of PTPN11 in tumor cells could increase PD-L1 expression in co-culture; in contrast, protecting tumor cells by overexpression of the SHP2 mutant impaired SHP099-induced PD-L1 upregulation." (PMID 33446805, 2021). "PTPN11 mutations E76K and G503V did not coexist in the same neoplasm." (PMID 31277422, 2019). "Clinical studies are warranted to understand whether neoplasms with or without PTPN11 mutation behave differently clinically (i.e. with regard to rate of disease progression, rate of metastasis, and prognosis)." (PMID 31277422, 2019). "Thus, in contrast to its common pro-oncogenic role in hematopoietic and epithelial cells, PTPN11 may act as a tumor suppressor in cartilage." (PMID 26768750, 2016). "In this setting, PTPN11 inhibition induced a shift in tumour microenvironment (TME) myeloid cell populations towards an inflammatory, anti-tumour phenotype, in part via effects on colony-stimulating factor 1 (CSF1) signalling pathways." (PMID 38334623, 2024). "For instance, tumor sample CCGA-UBC-034T contained an ecDNA with seven genes, including CDK4, DDIT3, GLI1, HMGA2, PTPN11, RFC5, and TMPO." (PMID 39267784, 2024). "This suggests similarity in gene expression between each tumor which may reflect the shared mutational profile, including activating FGFR1 variants, in addition to PIK3R1 variants predicted to activate the PI3K signaling pathway, in concert with the germline PTPN11 variant." (PMID 39309743, 2024). "For tumor suppressors that can also act as resistance or insensitivity factors, such as DAPK1 or PTPN11, the nature of perturbation or knock-out will substantially bias their activity and function." (PMID 38724493, 2024). "Antibody-mediated depletion of either CD4+ or CD8+ T cells diminished the anti-tumour effects of SHP099, suggesting an important role for T cell responses in the protective effects of PTPN11 inhibition." (PMID 38334623, 2024). "Among these, it was found that the three PTPs PTPN6, PTPN11 and PTPRO both induce drug resistance and alter inflammatory cytokine regulation, and these molecules can influence tumor growth and HCC progression." (PMID 36660927, 2023). "Altogether, these findings indicate the tumor-suppressive role of hsa-circ-0000221 in HCC, which acts through miR-661 inhibition, along with a subsequent PTPN11 mRNA increase, where PTPN11 is known to inhibit cell proliferation in many forms of cancer." (PMID 35057034, 2022). "On the other hand, deletion of PTPN11 enhances macrophage response to IFN-γ and increases production of the tumor cell-derived cytokine CXCL9, thereby promoting tumor infiltration of IFN-γ-producing T cells." (PMID 35957898, 2022). "LINC00673 promotes PTPN11 ubiquitination and degradation via mediation of an PRPF19–PTPN11 interaction, resulting into an elevated and STAT-dependent anti-tumor response." (PMID 34449663, 2021). "Compared with 12–12 genotype, the PTPN11 expression of 14–14 or 14–15 genotypes was dramatically increased in both HCC tissues and adjacent non-tumor tissues (fold change = 2.36 and 2.02, respectively, P<0.01)." (PMID 25198338, 2014). "Our results also demonstrated that PTPN11 expression was significantly higher in self-matched adjacent non-tumor tissues compared with that of HCC tissues (P<0.01), which validated the tumor-inhibiting effect of PTPN11 in HCC." (PMID 25198338, 2014). "Additionally, PTPN11-overexpressing and knockdown PTC cell lines, as well as xenograft tumor models in nude mice, will be constructed." (PMID 41367010, 2025).
tumor (continued). "Since previous cell-based experiments indicated that silencing of ARSB and the associated increase in chondroitin 4-sulfation enhanced the binding of SHP-2 (PTPN11) with C4S and reduced the SHP2 activity, the impact of exogenous ARSB on SHP2 in the tumor tissue was addressed." (PMID 37813168, 2024). "PTPN11 was moderately positive in most normal renal tissues according to CAB005377 staining (25-75% of glomerular and tubular cells were moderately stained) and was moderately positive in > 75% of the tumor tissues." (PMID 37056387, 2023). "Interestingly, NRAS alteration forms a Dual Lethal Dependency with PTPN11: it confers tumor sensitivity to NRAS inhibition and resistance to PTPN11 inhibition." (PMID 35805023, 2022). "In our present research, therefore, we evaluated the pan-cancer properties of PTPN11 by means of the TCGA project, GEO databases, the Clinical Proteomic Tumor Analysis Consortium (CPTAC), and the Human Protein Atlas (HPA) cohort in order to establish the link between PTPN11 expression and prognosis." (PMID 35802774, 2022). "We analyzed the expression levels of PTPNs in the TCGA database and discovered that PTPN1, PTPN6, PTPN7, PTPN18, PTPN20, and PTPN22 were significantly upregulated in tumor samples, while PTPN4, PTPN5, PTPN10, PTPN11, PTPN13, PTPN14, and PTPN21 were downregulated in tumor samples." (PMID 36226189, 2022). "In the reported patient, the tumor tissue had a PTPN11 VAF higher than that observed in noncancerous cutaneous overgrowth tissue, suggesting a clonal selection induced by the overactivation of the RAS/MAPK cascade." (PMID 35778969, 2022). "In mutant KRAS-driven murine models of NSCLC, genetic deletion of PTPN11 suppressed tumor development, while the dual inhibition of SHP2 and MEK resulted in sustained tumor growth control in murine- and human patient-derived organoids and xenograft models of NSCLC." (PMID 34885068, 2021). "Tyrosine phosphatase 2 (Shp2), which contains two homologous domains of Src, is a non-receptor tyrosine phosphatase encoded by the PTPN11 gene and is positively correlated with tumor metastasis." (PMID 34326840, 2021). "Moreover, the oncogenic gene PTPN11, which was significantly decreased by PLS-123, was identified as an additional anti-tumor mechanism of this novel Btk inhibitor." (PMID 25944695, 2015). "This co-transfection produced obvious anti-proliferative activity towards tumor cells, suggesting that PLS-123 might suppress tumor growth through combination Btk and PTPN11 inhibition." (PMID 25944695, 2015). "Conversely, proteins hypophosphorylated (Tumor/Normal phosphorylation spectral count ratio >1) in tumors include the transcription factors STAT1 and STAT5, the protein tyrosine phosphatase PTPN11, the G-protein coupled receptor GPRC5A, and the kinases MAPK1, MAPK3, and TNK2." (PMID 19946374, 2009). "In contrast, T cell-specific deletion of Ptpn11 does not improve T cell anti-tumour responses, indicating that the effects of PTPN11 inhibitors on T cell responses in cancer settings are likely to be indirect and secondary to the modulation of myeloid cell phenotypes." (PMID 38334623, 2024). "LINC00673 may also act as a tumor suppressor by promoting interaction between protein tyrosine phosphatase, non-receptor type 11 (Ptpn11) and ubiquitin ligase, resulting in degradation of Ptpn11 and lowered oncogenic signaling." (PMID 31178901, 2019). "Independent of HB tumor location PTPN11 may act as tumor suppressor or oncogene depending on the tumor cell of origin." (PMID 26768750, 2016). "Finally, the expression level of PTPN11 in adjacent non-tumor tissues was 2.39-fold higher than that of HCC tumor tissues." (PMID 25198338, 2014). "Besides, PTPN11 could activate the Ras/Erk/MAPK signaling pathway by dephosphorylating Ras to promote cell proliferation, and activation of Ras/Erk pathway could reduce the levels of TILs, which promotes the immune escape by the tumor cells." (PMID 35802774, 2022).
tumor (continued). "Therefore, it is possible that IKZF1 could work as a negative transcriptional regulator of the RAS pathway by binding to the PTPN11 promoter and directly suppressing its activity, and thus tumor cells may not need both altered pathways to drive disease relapse." (PMID 39766099, 2024). "Studies demonstrated that an allosteric PTPN11 inhibitor, RMC-4550, reduced CT26 tumour growth in immunocompetent mice but not in recombinase activating gene 2 (RAG2)-deficient mice, indicating a requirement for adaptive lymphocytes in mediating the protective effect." (PMID 38334623, 2024).
cancer (441 papers, 2008 to 2026). A tumor composed of atypical neoplastic, often pleomorphic cells that invade other tissues. "Missense mutations in PTPN11, which encodes the protein tyrosine phosphatase SHP2, are common in several developmental disorders and cancers." (PMID 40661614, 2025). "Amid the NCH cohort, 4 of 314 individuals (1.3%) who underwent genomic profiling as part of an institutional translational cancer protocol harbored a germline variant in PTPN11 associated with NS." (PMID 39309743, 2024). "SHP2 activity has been connected to a number of cancer types in addition to cancers brought on by PTPN11 mutations." (PMID 37344519, 2023). "The human PTPN11 gene encodes for the src tyrosine phosphatase protein (SHP2) is now gaining much attention in many disorders, particularly its oncogenic involvement in many types of cancer." (PMID 37513838, 2023). "The cancer-associated PTPN11 mutations target two hotspots at the N-SH2 and PTP domains, respectively, that mostly result in an increased phosphatase activity or in a reduced threshold for SHP2 activation." (PMID 36755664, 2022). "Recurrent mutations in the PTPN11 gene encoding SHP2 have been observed in a variety of human cancers; therefore, SHP2 is thought to be a promising therapeutic target." (PMID 35954414, 2022). "In the current study, PTPN11 mutation patterns were examined across various human cancers by cBioPortal tool and the results indicated PTPN11 was mutated in most cancers." (PMID 35802774, 2022). "The cancer- and NS-associated mutations in PTPN11 occur at the interface between the N-terminal SH2 domain at residues D62, Y63 or Q79, and in the PTP domain at residue N308, and relieve auto-inhibitory intramolecular interactions." (PMID 35178568, 2022). "Previous work has suggested that PTPN11 mutations were associated with genetic developmental diseases and cancers." (PMID 35802774, 2022). "We detected 14 heterozygous variants within the coding regions of 13 cancer- and other disease-related genes, including single-base substitutions in the PTPN11 (c.1508G > T, p.Gly503Val) and BRAP (c.1109G > C, p.Gly370Ala) genes." (PMID 35625983, 2022). "The identified E69K mutation is recurrent according to COSMIC (cancer.sanger.ac.uk), and is predicted to activate PTPN11." (PMID 36097178, 2022). "Our data indicate that the combination of NF1 mutation and PTPN11 mutation drives the malignancy of NF1 cells and that SHP-2 inhibition by BRAP is a potential therapeutic strategy for NF1-associated malignant tumors." (PMID 35625983, 2022). "In many cancer types, SHP2 is hyperactive due to mutations of the Ptpn11 gene, which encodes SHP2, or to aberrant signaling from protein tyrosine kinases, and functions as a proto‐oncogene." (PMID 34102002, 2021). "PTPN11 is also the first proto-oncogene identified as encoding tyrosine phosphatase, one of the hotspots in the cancer research area." (PMID 34167452, 2021). "In additionto malignancies driven by PTPN11 mutations, severalforms of cancer are linked to the activity of wild-type SHP2." (PMID 34714648, 2021). "Specifically, somatic PTPN11 mutations in patients with multiple cancer types including leukemias, breast cancer and gastric cancer have been genotyped." (PMID 30429852, 2018). "PTPN11 was also upregulated in carcinoma tissue, as were the majority of miRNAs associated with this gene." (PMID 30603058, 2018). "Germline mutations of PTPN11 have been previously associated with Noonan and Leopard Syndromes, with an increased risk of developing cancer." (PMID 27168466, 2016). "In fact, on the basis of the study of recurrent mutations in interaction interfaces, PTPN11 has recently been suggested to be a cancer driver." (PMID 26886259, 2016). "Mutations in the PTPN11 gene are associated with various developmental disorders, hematologic malignancies, and solid tumors, playing distinct biological roles in different mechanisms of cancer development." (PMID 38025540, 2023).